BAP1 (BRCA1 associated deubiquitinase 1)
Diseases named in the same sentence as BAP1 in open-access papers (continued):
Sharing a sentence is not in itself a finding about the gene and the disease.
tumor (continued). "The effects of BAP1 loss on EMT and tumor immune escape should be further investigated." (PMID 38987362, 2024). "However, VHL mutation, SETD2 mutation and BAP1 mutation had mutational differences of up to 10% between the two groups, suggesting that differential expression of BID mediates differential tumor mutational signatures." (PMID 38767695, 2024). "We previously reported that patients treated with the PD-1 inhibitor pembrolizumab and the histone deacetylase inhibitor entinostat in the PEMDAC trial, experienced clinical benefits if their tumor originated from iris or was wildtype for BAP1 tumor suppressor gene." (PMID 37377898, 2023). "BRCA1, BRCA2, ATM, PALB2, and BAP1 were the DNA damage response GA found in our tumor samples." (PMID 36831055, 2023). "Therefore, respective roles of chromosome 3 status/BAP1 status and pigmentation in the development of an immune response against the tumor should be explored further." (PMID 37193315, 2023). "Various oncogenic signaling cascades have been found to conduct the symphony of ferroptosis in malignant cells, and ferroptosis intersects with the functionalities of numerous tumor suppressors, such as the retinoblastoma protein (RB1) and the breast cancer 1 (BRCA1)-associated protein 1 (BAP1)." (PMID 37840106, 2023). "We further validated the crucial role of BAP1 in tumor promotion by regulating MYCN." (PMID 37543638, 2023). "Our results indicate that this model (BPS-TA) induces low numbers of somatic mutations in Bap1 and Pbrm1 (but not in Setd2), known tumor suppressor genes in human ccRCC." (PMID 37217526, 2023). "These activities make BAP1 a powerful tumor suppressor, and improving our understanding of its mechanisms could point the way to new cancer treatments." (PMID 37009801, 2023). "MeT5A-BAP1w-/KO have stably reduced BAP1 expression and, given that BAP1 mutation is an early truncal change, represent a more relevant model to study tumor biology and drug sensitivity than modulation of BAP1 in established cancer cell lines that already harbor a spectrum of tumorigenic mutations." (PMID 36669126, 2023). "Collectively, these results show a significantly higher infiltration with CD8 + TILs in BAP1- or PTEN-mutated ccRCCs both at the invasive margin and in the tumor periphery, while counts for CD4 + or FOXP3 + cells were found to depend more on the histological subtype than the mutational status." (PMID 36562826, 2023). "BAP1, another tumor suppressor, also sensitizes ferroptotic tumor cell death by repressing the amino acid antiporter system Xc- expression, which is important for synthesizing cellular reduced glutathione (GSH) to protect lipids from peroxidation and ferroptosis." (PMID 37325669, 2023). "Genomic analysis of the clinical tumor and PDX revealed gains in chromosome 1q and chromosome 3, as well as a loss of heterozygosity (LOH) in chromosome 3 involving the 3p21.1 band, which includes the BAP1 gene, in both tumors." (PMID 37158111, 2023). "A lot of studies have revealed that the mutation of BAP1 is associated with poor prognosis even though how PBRM1 gene mutations promote carcinogenesis and tumor progression is still unknown." (PMID 37427096, 2023). "We also analyzed DACRs for PBRM1 mutants (9 tumors, not including 2 with both BAP1 and PBRM1 mutations) versus tumors without PBRM1 or BAP1 mutations (again using only tumor cells)." (PMID 36973268, 2023). "BRCA1-associated protein 1 (BAP1), a ubiquitin carboxy-terminal hydrolase identified as a tumor suppressor, can regulate multiple processes including immune response; BAP1 mutations could lead to the occurrence of aggressive cancers such as UM." (PMID 37710185, 2023).
tumor (continued). "In addition, a single small study of six tumours from two patients demonstrated an increased growth rate of tumours in BAP1 carriers." (PMID 37607989, 2023). "Recent work has shown that BAP1 biallelic inactivation could promote metastasis development by enhancing immune evasion of the tumor through inhibition of the immune response, consistent with the limited response of UM to immunotherapy." (PMID 37958591, 2023). "From this model it will, however, remain unclear if the mutations in BAP1 and CDKN2A were conserved from the originating tumor or acquired during passaging in the commercial cell lines." (PMID 37345150, 2023). "In addition to other factors, the deubiquitinating enzyme BAP1 is a tumor suppressor in cholangiocarcinoma." (PMID 37547759, 2023). "Furthermore, these tumours have an unfavourable EMT profile and are associated with monosomy of chromosome 3/loss of BAP1 expression." (PMID 37240204, 2023). "We confirm that dark tumors carry a worse prognosis than light tumors and report a significant association between dark tumor pigmentation and negative genetic prognostic factors: monosomy of chromosome 3, loss of BAP1 expression, and gain of chromosome 8q." (PMID 37193315, 2023). "BAP1 inhibits tumor development, in part, via SLC7A11 and ferroptosis." (PMID 37061535, 2023). "The complement factor H-related (CFHR) protein family induces the ubiquitination of polo-like kinase 1 (PLK1) at lysine 209, BRCA1-associated protein 1 (BAP1) enhances genomic stability, and USP9X is found to restrain tumor growth in the patient-derived tumor xenograft (PDX) model." (PMID 38174069, 2023). "Therefore, we set out to compare histopathologic tumor characteristics, chromosome 3 and 8q status, and BAP1 expression in tumors with different pigmentation levels." (PMID 37193315, 2023). "Recently, accumulating evidence have revealed that BAP1 mutations are frequently found in different cancer types which indicated that BAP1 might be a critical tumor suppressor." (PMID 37543638, 2023). "If a similar mechanism, possibly initiated by BAP1 inactivation, is present in UM as well, it may partially explain the different behaviour of tumours with high and low MITF." (PMID 37240204, 2023). "Interestingly, ASS-1 protein and mRNA levels have recently been shown to be dependent on BRCA-associated protein 1 (BAP1) levels in MPM cells and tumours." (PMID 39516654, 2023). "Furthermore, BAP1 knockdown inhibits NB tumor cells growth and migration in vitro and in vivo, which can be rescued partially by ectopic expression of MYCN." (PMID 37543638, 2023). "Furthermore, the weight of tumor plus kidney exhibited a consistent result with subcutaneous xenograft that BAP1 depletion markedly reduced the weight but overexpression of MYCN partially rescued BAP1 depletion-caused weight reduction." (PMID 37543638, 2023). "In addition, the MBD5 and MBD6 subunits are critical for maintaining the stability of the BAP1 complex and therefore are essential for BAP1-dependent tumor cell growth in vitro and in vivo." (PMID 36180891, 2022). "Most of the earlier studies demonstrated that BAP1 exerts a tumor suppressive function." (PMID 36003792, 2022). "Depletion of BAP1 or treatment with BAP1-specific inhibitors could significantly reduce SCLC tumor growth in vitro and in vivo." (PMID 36180891, 2022). "Examination of the TCGA database also showed that the level of Bap1 mRNA was lower in the lung tissues of human LUAD compared with those of normal people and it was associated with an increase in the survival of LUAD patients at tumor stages II–IV." (PMID 35052618, 2022).
tumor (continued). "Tumorigenesis is not expected to occur without the loss of BAP1 function in the majority of class-2 tumors, thus, cells expressing nBAP1 are more likely to be non-tumor cells, such as macrophages or melanophages." (PMID 36077643, 2022). "BAP-1 overexpression has been shown to decrease tumor cell proliferation both in vivo and in vitro." (PMID 35408533, 2022). "BRCA1-Associated Protein 1 (BAP1) is a deubiquitylase that is found associated with multiprotein complexes that regulate key cellular pathways, and subsequent researches have revealed that BAP1 acts independently as a tumor suppressor." (PMID 34976173, 2022). "Frequent inactivation of the tumour suppressors BAP1, NF2 and P16 may differentially sensitise tumours to treatments." (PMID 36497318, 2022). "The loss of BAP1 can upregulate the expression of immunological genes, such as HLA-DR, HLA class II, and CD38, correlated with immunosuppressive cells infiltrating the tumor microenvironment." (PMID 36012262, 2022). "Currently, prognosis of patients with UM is based on clinical, anatomic, and morphologic parameters of the tumor cells, combined with their genetic features (e.g., M3, polysomy 8q, the gene expression profile, and the presence/absence of BAP1 mutations)." (PMID 35348598, 2022). "This provides a feasible possibility that BAP1 might provide a clinical benefit to LUAD patients at higher tumor stages." (PMID 35052618, 2022). "Moreover, the tumor suppressor gene, BRCA1-associated protein 1 (BAP1), was found to reduce SLC7A11 expression by decreasing histone 2A ubiquitination occupancy on its promoter in human cancer, which consequently resulted in increased ferroptosis." (PMID 35531466, 2022). "There were contradictory evidences supporting the tumor suppressor role of BAP1 in cancer." (PMID 34976173, 2022). "We have recently shown that depletion of BAP1 by CRISPR or treatment with BAP1 inhibitors could reduce SCLC tumor growth in vitro and in vivo." (PMID 36180891, 2022). "Initially, BAP1 has been characterized as a tumor suppressor in animal models." (PMID 35194152, 2022). "Percent tumor cell staining was recorded (Glut-1, CD5, CD117); loss of expression (BAP1, mTAP) was considered if essentially all tumor cells were negative; TdT was recorded as thymocytes present or absent (including rare thymocytes)." (PMID 35565429, 2022). "Wildtype BAP1 was shown to inhibit cystine uptake, leading to ferroptosis and tumor suppression." (PMID 35307036, 2022). "Thus, by applying additional chemical modifications and small-scale screenings, we have identified a next-generation BAP1 inhibitor, which shows a more robust activity, specificity, and anti-tumor effects than the original version." (PMID 35194152, 2022). "Next, we performed IHC on the proband’s tumor tissues to evaluate BAP1 status." (PMID 35885614, 2022). "Previous studies have demonstrated that transcriptional and post‐transcriptional suppression of SLC7A11 by transcription factors (such as ATF3 and ATF4), H2A deubiquitinases (such as BAP1), and epigenetic modifications (such as H2Bub1) can promote erastin‐induced tumour cell ferroptosis." (PMID 35522946, 2022). "A tumor suppressor gene called BAP1 codes for ubiquitin carboxy-terminal hydroxylase BAP1." (PMID 35465855, 2022). "BAP1 is a deubiquitinating enzyme with an increasingly recognized role in tumor suppression." (PMID 35349481, 2022). "Supporting this speculation, we observed that the levels of Bap1 and Keap1 mRNA were progressively decreased in the lung tissues of KrasG12D/+ mice, compared with those of wild-type littermates during tumor progression." (PMID 35052618, 2022).
tumor (continued). "The majority of tumor samples with likely pathogenic BAP1 mutations, regardless of mutation class, displayed ≥25% loss of nBAP1." (PMID 36077643, 2022). "The most common alterations were BAP1 mutations (n = 5; of note, BAP1 was assessed only by the 14MG panel and only in the tumour specimen, no germline analysis), CDKN2A loss (n = 2) and NF2 mutation (n = 2; to note, NF2 was assessed only by the 14MG panel)." (PMID 35585228, 2022). "Because of this, BAP1 may act as a natural tumor suppressor gene, inhibiting the development of tumors." (PMID 35408533, 2022). "Furthermore, immunohistochemistry staining data obtained from the HPA validated BAP1 downregulation in tumor tissue." (PMID 35425712, 2022). "Interestingly, the loss of BAP1 was associated with apoptosis in a large set of cell types, but not in melanocytes and mesothelial cells, where its inactivation favored tumorigenesis, demonstrating a cell-specific tumor suppressor function of BAP1." (PMID 33800394, 2021). "Encouraging positive responses in terms of progression-free survival (PFS) and OS were observed in a well-defined subset of mestastic UM patients, namely, patients with BAP1-preserved tumours and one patient with iris melanoma containing a UV-related gene signature." (PMID 35008260, 2021). "The primary tumor and metastases were immunohistochemically examined using BAP1 antibody." (PMID 34885018, 2021). "BAP1 is a tumor suppressor and regulates chromatin accessibility." (PMID 33805113, 2021). "We then asked whether methylation levels of BAP1 could be employed as a surrogate of the preponderance of tumor subclones with high metastatic potential." (PMID 34593944, 2021). "In conclusion, novel significant associations among different BAP1 staining patterns and subgroups of MPM tumors were observed, suggesting that the role of BAP1 in tumor progression may be more complex than its presumed tumor suppressor function." (PMID 32944962, 2021). "The mean proportion of BAP-1 positive cells in full tumor sections was 47% (SD 36)." (PMID 33800007, 2021). "The volume of BAP1 mutant cells can be described as a function of tumor volume." (PMID 33903674, 2021). "This evidence confirms that BAP1 behaves as a tumor suppressor." (PMID 33802313, 2021). "Furthermore, BAP1, a member of the UCHs subfamily, is predominantly located in the nucleus and functions as a tumour suppressor." (PMID 34177595, 2021). "BAP1 acts as tumor suppressor and is involved in many crucial cellular processes." (PMID 33800394, 2021). "Similarly, BAP-1 expression in any tumor region added significant prognostic information to gene expression class (LRΔχ2 4.1 to 12.0, p < 0.001 to 0.04)." (PMID 33800007, 2021). "Recently, BAP1 was found to link ferroptosis to tumor suppression." (PMID 34830866, 2021). "The mean proportion of BAP-1 positive cells in tumor cold spots was 27% (SD 32)." (PMID 33800007, 2021). "In this study, we demonstrated that BAP1 acted as a tumor suppressor in PCa progression." (PMID 33155366, 2021). "Despite BAP1 being a well-known tumor suppressor gene, the mechanisms by which BAP1 exerts its tumor suppressor function remain unclear." (PMID 33499222, 2021). "Notably, we observed that BAP1 knockdown contributed to PCa cells migration, invasion, transformation, and tumor growth." (PMID 33155366, 2021).
tumor (continued). "Although genetic depletion of BAP1 could lead to leukemogenesis in vivo, emerging studies have identified that BAP1 may also be required for tumor cell viability." (PMID 33483476, 2021). "The mean proportion of BAP-1 positive cells in tumor hot spots was 66% (SD 35)." (PMID 33800007, 2021). "Importantly, cancer-associated BAP1 mutations are defective in SLC7A11 regulation and ferroptosis, suggesting that SLC7A11-mediated ferroptosis has a role in the tumor-suppressive function of BAP1." (PMID 33499222, 2021). "This indirect regulation of transcription and chromatin conformation may help explain the tumor-suppressive functions of BAP1." (PMID 34186021, 2021). "Finally, patients are considered high risk if their tumor is GEP class 2, has monosomy 3 or gain of chromosome 8q, harbors a BAP1 mutation, has PRAME expression, or is T4 based on AJCC guidelines." (PMID 34771666, 2021). "Loss of heterozygosity (LOH) for chromosome 3, which unmasks BAP1 mutations in metastasizing Class 2 UM3, was detected in all tumor samples for both patients, consistent with a canonical aberration that arises early in tumor evolution." (PMID 34400647, 2021). "We then sought to test whether BAP1 methylation values, surrogates of the preponderance of aggressive tumor subclones, could also offer prognostic information." (PMID 34593944, 2021). "To further determine whether BAP1 function of tumor suppression is dependent on inhibiting the Akt signaling pathway, we silenced Akt1 by lenti‐shRNAs in DU145‐shBAP1‐1# cells." (PMID 33155366, 2021). "Consequently, with a doubling time of 511 days, the first tumor cell with lost BAP1 expression appeared when the tumor was 767 to 1665 days or 2.1 to 4.6 years old." (PMID 33903674, 2021). "Given that suppressed IP3R3-mediated Ca2+ flux and apoptosis has been linked to other major tumor suppressors PTEN, BAP1, and PML, in driving tumorigenesis, our above analyses suggest that this may also play a role in SMARCA4/2-deficient cancers." (PMID 34518526, 2021). "Cases were classified according to the BAP1 staining pattern of tumor cells." (PMID 32944962, 2021). "This raises the possibility that BAP1 may function as a tumor suppressor also in the B cell lineage." (PMID 33912157, 2021). "When constitutively expressing wild-type BAP1, cell proliferation significantly decreased and cells were less able to form colonies and proliferate when seeded at low density, which is in line with the known role of BAP1 as a tumor suppressor." (PMID 34201614, 2021). "The highest frequency of chromosome 3p deletion, locus of MST1R and BAP1, indicated that the inactivation of tumor suppressor genes in this chromosome might be an early event contributing to transformation from nasopharyngeal epithelium to NPC." (PMID 34031426, 2021). "The result demonstrated a key aspect of BAP1’s tumor suppressor function." (PMID 33805113, 2021). "We hypothesize that vasculogenic mimicry in tumor regions with high proportions of BAP-1 mutant cells increases metastatic spread by providing a tumor architecture that promotes dissemination." (PMID 33800007, 2021). "The BAP1 gene codifies the BAP1 protein which has a tumor suppressor function." (PMID 34771510, 2021). "If only a smaller portion of a tumor is sampled for prognostic testing including assessment of level of BAP-1 expression, the presence of such heterogeneity may impact the results significantly." (PMID 33800007, 2021). "The BRCA1-associated protein 1 (BAP1) complex was initially identified as a major histone H2A lysine 119 (H2AK119) deubiquitinase in drosophila and was then further characterized as a tumor suppressor in leukemogenesis." (PMID 32669118, 2020).